PRTN3 (proteinase 3)
Diseases named in the same sentence as PRTN3 in open-access papers (continued):
Sharing a sentence is not in itself a finding about the gene and the disease.
Autoimmunity (34 papers, 2011 to 2026). The occurrence of an immune reaction against the organism's own cells or tissues. "Anti-neutrophil cytoplasmic antibody (ANCA)-associated vasculitis (AAV) is a systemic autoimmune condition characterised by inflammation of small vessels, primarily driven by ANCAs targeting proteinase 3 (PR3) or myeloperoxidase (MPO)." (PMID 41222744, 2025). "Considering the ROC analysis results of serum MPO‐ANCA, higher diagnostic sensitivity and specificity of serum PR3‐ANCA may be due to the stronger stimulation of the infectious antigen by proteinase‐3‐related autoimmunity." (PMID 37872840, 2023). "It is caused by autoimmunity against neutrophil proteins, mainly myeloperoxidase (MPO) and proteinase-3 (PR3)." (PMID 34394071, 2021). "At the age of 17, signs of autoimmunity were detected, with the presence of autoantibodies against proteinase 3 (cANCA) in the patient’s serum." (PMID 22952854, 2012). "Although the precise etiology of the disease is unknown, immune dysregulation and autoimmunity are heavily implicated, with the characteristic presence of antineutrophil cytoplasmic antibodies (ANCA) against proteinase 3 (PR3) in patients with GPA." (PMID 40062629, 2025). "There is now renewed attention on neutrophils and neutrophil serine proteases (NSPs) such as neutrophil elastase (NE), proteinase 3 (PR3), and cathepsin G (CG) in inflammation and autoimmunity." (PMID 28192517, 2017). "Similar to ICs in SLE patients, ANCAs directed against proteinase-3 (PR3) and MPO can stimulate neutrophils in SVV to form NETs and promote autoimmunity." (PMID 23355837, 2013). "One hypothesis is that hydralazine decreases DNA methyltransferase expression and induces autoimmunity by inhibiting extracellular signal-regulated kinase (ERK) pathway signaling and that may be responsible for disrupting the suppression of proteinase 3 (PR3) and MPO." (PMID 32290867, 2020).
COVID-19 (26 papers, 2020 to 2026). A disease caused by infection with severe acute respiratory syndrome coronavirus 2. "To validate our in-silico analysis, we measured plasma protein levels of two autoantigens, MPO and PRTN3, in severe and asymptomatic COVID-19." (PMID 34276672, 2021). "To validate our in-silico analysis, we next measured plasma protein levels of two autoantigens of MPO and PRTN3 in severe and asymptomatic COVID-19." (PMID 34276672, 2021). "ProNETosis gene signatures were observed in both pro- (MPO, ELA, and PRTN3) and pre-(PADI4) neutrophils and were associated with COVID-19 severity." (PMID 34616409, 2021). "As COVID-19 is associated with pulmonary and vascular manifestations, we also investigated autoantibodies targeting myeloperoxidase (MPO), proteinase 3 (PR3) and glomerular basement membrane (GBM)." (PMID 33263103, 2020). "However, we cannot exclude the involvement of other proteases such as neutrophil elastase, which was recently published in COVID-19 patients, as well as serine proteases such as proteinase 3, cathepsins, and ADAMs from neutrophils." (PMID 37569899, 2023). "Interestingly, enhanced expression and circulation of autoantigens like MPO or PRTN3 has also been observed in COVID-19 patients, and the levels of expression of some of these autoantigens correlate with disease severity." (PMID 34512643, 2021). "The neutrophil proteases PRTN3 (proteinase-3) and MPO (myeloperoxidase) and the neutrophil-derived protein AZU1 were associated with severe disease, indicating that neutrophil activation and degranulation are features of severe COVID-19." (PMID 33704068, 2021). "In contrast, G-MDSC from severe COVID-19 patients had increased expression of genes associated with granulocyte functions/degranulation and chronic inflammation including Arg1, MMP8, MMP9, S100A8 and A9, MPO, IL18RA, elastase, PRTN3 (azurophilic granule protein 7)." (PMID 34341659, 2021). "Comparison of COVID-19 blood transcriptomic with IAV and RSV revealed that MPO, PRTN3, and PADI4 were selectively upregulated in coronavirus infections, SARS-CoV-1 and SARS-CoV-2, while TSHR and PTPRN2 autoantigens were distinctive to SARS-CoV-2 infection." (PMID 34276672, 2021). "The level of three autoantigens, MPO, PRTN3, and PADI4, were higher in the blood of severe compared to mild COVID-19." (PMID 34276672, 2021). "In whole blood study, seven autoantigens were upregulated in blood of severe COVID-19 patients (MPO, PRTN3, PADI4, IFIH1, TRIM21, PTPRN2, and TSHR), while four autoantigens (MPO, PRTN3, IFIH1, and PADI4) were increased in blood of mild patients." (PMID 34276672, 2021). "These cells had a significantly high level of MPO, PRTN3, and PADI4 indicating that they could be a major source of the observed increase in blood level of these autoantigens during severe COVID-19." (PMID 34276672, 2021). "Furthermore, the genes ELANE, AZU1, MPO, PRTN3, CTSG, and TCN1 were shown to be significantly altered in patients with COVID-19, and our automatically prepared knowledge base highlights all of them as associated with COVID-19 with “medium” or “low” confidence." (PMID 33055059, 2020).
Granuloma (24 papers, 2014 to 2025). A compact, organized collection of mature mononuclear phagocytes, which may be but is not necessarily accompanied by accessory features such as necrosis. "The patient was diagnosed with GPA and non-infectious endocarditis, DAH, and RPGN, based on a biopsy which revealed pauci-immune crescentic glomerulonephritis with granuloma and leukocytoclastic vasculitis and antineutrophil cytoplasmic antibodies against proteinase 3- positivity." (PMID 31860960, 2019). "The pathogenic hallmark of GPA is the loss of immune tolerance by T and B cells to neutrophil-derived proteins - primarily proteinase 3 (PR3) or myeloperoxidase (MPO) - leading to inflammation of vessel walls and the formation of peri- and extravascular granulomas." (PMID 40918843, 2025).
ulcerative colitis (21 papers, 2013 to 2025). An inflammatory bowel disease involving the mucosal surface of the large intestine and rectum. "Proteinase 3 antineutrophil cytoplasmatic antibodies (PR3-ANCA) have been shown to discriminate patients with ulcerative colitis from those with Crohn’s disease, along with demonstrating disease severity and activity." (PMID 39202232, 2024). "Recent reports have shown that antibodies to proteinase-3 (PR3-ANCA) might add diagnostic value in inflammatory bowel disease (IBD), specifically in ulcerative colitis (UC)." (PMID 25397578, 2014).
crescentic glomerulonephritis (20 papers, 2008 to 2025). A histopathologic term for a pattern of diseases characterized by extensive crescent formation in the glomeruli; patients present clinically with rapid deterioration of renal function, and possible progression to end-stage renal failure within weeks or months. "In elderly people, myeloperoxidase (MPO) and proteinase-3 (PR3) antineutrophil cytoplasmic antibody (ANCA)-associated crescentic glomerulonephritis (CGN) is a major cause of rapidly progressive glomerulonephritis (RPGN)." (PMID 22656245, 2012). "We present a case of a 44-year-old male whose biopsy demonstrated crescentic glomerulonephritis, pauci-immune type proteinase 3 antineutrophil cytoplasmic antibody (PR3-ANCA) consistent with GPA, as well as profound proteinuria, an atypical manifestation." (PMID 35572457, 2022). "Pathogenic ANCAs, in particular proteinase 3 (PR3) and myeloperoxidase (MPO), trigger a deleterious immune response resulting in a pauci-immune necrotizing and crescentic glomerulonephritis (GN), a common manifestation of glomerular injury in AAV." (PMID 34759920, 2021). "Pathogenic ANCAs, in particular proteinase 3 (PR3) and myeloperoxidase (MPO), trigger a deleterious immune response resulting in pauci-immune necrotizing and crescentic glomerulonephritis (GN), a common manifestation of glomerular injury in AAV." (PMID 34205415, 2021). "Pathogenic ANCAs, in particular proteinase 3 (PR3) and myeloperoxidase (MPO), trigger a deleterious immune response with intrarenal immune cell infiltration resulting in a pauci-immune necrotizing and crescentic glomerulonephritis (GN)." (PMID 34759920, 2021). "Nine patients had high-titer autoantibodies (six with myeloperoxidase [MPO]-ANCA, two with proteinase 3 [PR3]-ANCA, and one with anti-phospholipase A2 receptor [PLA2R] antibody) and were diagnosed with crescentic glomerulonephritis (CrGN)." (PMID 34692728, 2021). "Despite the paucity of immunoglobulin deposition in the glomeruli, this form of crescentic glomerulonephritis is correlated with circulating anti-neutrophil cytoplasmic antibodies (ANCA), which are largely specific for two neutrophil constituents, proteinase-3 or myeloperoxidase (MPO)." (PMID 25964886, 2015).
leukemia (19 papers, 2007 to 2025). A malignant (clonal) hematologic disorder, involving hematopoietic stem cells and characterized by the presence of primitive or atypical myeloid or lymphoid cells in the bone marrow and the blood. "To study antigen-specific T cells in CML, we chose PR1, a leukemia-associated antigen from proteinase 3 (PRTN3) and neutrophil elastase (ELANE) genes, as anti-PR1 T cells have been associated with response to TKI and successful IFN-α discontinuation." (PMID 37919606, 2024). "PRTN3 is one of the primary components of neutrophil azurophilic granules and a leukemia-associated antigen specifically recognized by CD8+ cytotoxic T-lymphocytes (CTLs)." (PMID 37231509, 2023). "Human proteinase 3 (PRTN3) is a leukemia-associated antigen." (PMID 35111390, 2022). "A decrease in the number of natural killer (NK) cells and cytotoxic T-lymphocytes (CTLs), and impaired responses to leukemia-associated antigens WT1, proteinase 3, BMI-1, and preferentially expressed antigen of melanoma (PRAME) were observed at diagnosis." (PMID 34771599, 2021). "CML cells express both leukemia-specific antigen derived from the BCR-ABL fusion protein and leukemia-associated antigens, including Wilms tumor 1(WT1), proteinase 3 (PR1), and preferentially expressed antigen of melanoma (PRAME)." (PMID 34771599, 2021). "Downregulation of PRTN3 has also been reported to inhibit proliferation and induces differentiation of promyelocyte-like leukemia cells." (PMID 29515771, 2018). "Other attractive LAAs, including WT1 antigen, proteinase-3 peptide, PRAME, and RHAMM, which are self-antigens overexpressed in leukemia cells, can also serve as leukemia-associated targets for immune responses." (PMID 23394714, 2013). "A number of groups are investigating the use of T cells specific to the leukemia antigens such as Wilms tumor 1 (WT1) and proteinase 3 (PR3) to prevent or treat leukemia relapse following HSCT." (PMID 21740581, 2011). "It is known that AML cells express leukemia-associated antigens (LAA) that can be recognized by the immune system, including those derived from proteins such as proteinase 3 (PR3), receptor for hyaluronic acid-mediated motility (RHAMM), and Wilm’s tumor-1 (WT1), among others." (PMID 25914882, 2015).
anemia (16 papers, 2014 to 2026). A reduction in the number of red blood cells, the amount of hemoglobin, and/or the volume of packed red blood cells. "Serological lab tests revealed inflammatory syndrome, leukocytosis, moderate anemia, and elevated anti-neutrophil cytoplasmic antibody titers with positive reactions against proteinase-3 (PR3-cANCA)." (PMID 39857028, 2025).
Crohn disease (16 papers, 2013 to 2025). A gastrointestinal disorder characterized by chronic inflammation involving all layers of the intestinal wall, noncaseating granulomas affecting the intestinal wall and regional lymph nodes, and transmural fibrosis. "Recent studies have demonstrated proteinase 3 antineutrophil cytoplasmic antibody (PR3-ANCA) to be a serological marker for differentiating UC from Crohn's disease in children and for detecting disease activity and nonresponse to steroid therapy and antitumor necrotizing factor-α agents." (PMID 35281249, 2022).
eosinophilia (16 papers, 2014 to 2026). "These criteria primarily rely on factors such as respiratory and kidney involvement, blood eosinophilia, and anti-proteinase 3 (PR3) antibody status to distinguish EGPA from other polyangiitis." (PMID 38699219, 2024). "Laboratory testing showed marked eosinophilia and positivity for proteinase 3 (PR3) c-ANCA." (PMID 41835779, 2026). "Increasing evidence suggests overlapping features, particularly in proteinase 3 (PR3)-ANCA-positive EGPA and GPA with eosinophilia." (PMID 41366827, 2025).
acute kidney injury (15 papers, 2008 to 2026). Sudden and sustained deterioration of the kidney function characterized by decreased glomerular filtration rate, increased serum creatinine or oliguria. "A “triple positive” disease (anti-GBM, myeloperoxidase (MPO), and proteinase 3 (PR3)) causing an isolated renal failure is even rarer." (PMID 36419545, 2022). "We report a case of acute kidney injury with positive proteinase 3 (PR3)-ANCA and anti-GBM, both of which were ultimately found to be false positives in the setting of infective endocarditis." (PMID 40630299, 2025). "Our case of triple-positive disease is an even rarer cause of isolated renal failure, as it includes anti-GBM, antimyeloperoxidase (MPO), and antiproteinase 3 (PR3)." (PMID 36419545, 2022). "Acute kidney injury was seen in two patients with combined positivity for anti-myeloperoxidase and anti-proteinase 3 antibodies, though neither patient progressed to the point of requiring renal replacement therapy." (PMID 26635879, 2015).
Sjögren’s syndrome (14 papers, 2013 to 2025). "Garreto and colleagues also revealed a significant increase in the levels of Matrix Metalloproteinase-9 (MMP9), Neutrophil Elastase (ELANE), Cathepsin G (CTSG), and Myeloblastin (PRTN3) in the saliva of patients with Sjögren’s syndrome compared to healthy controls." (PMID 41301757, 2025).
tuberculosis (14 papers, 2008 to 2025). A chronic, recurrent infection caused by the bacterium Mycobacterium tuberculosis. "Proteinase 3 anti-neutrophil cytoplasmic antibody may be a valuable diagnostic marker in patients with atypical symptoms of granulomatosis with polyangiitis or in the presence of probable tuberculosis." (PMID 26714880, 2015). "To examine the effect of anti-tuberculosis treatment (ATT) on neutrophil granular proteins (MPO, PRTN3, elastase), we have analyzed their pre and post-treatment systemic levels among TBL individuals." (PMID 34153068, 2021).
diabetes (13 papers, 2019 to 2025). "Moreover, PRTN3, encoding proteinase 3—a neutrophil serine protease—is consistently upregulated and correlates with neutrophil activity, serving as a shared biomarker for both IDD and diabetes mellitus, suggesting a role for neutrophil‐mediated inflammation in the comorbidity of these diseases." (PMID 41357670, 2025). "Given the consistent expression trends of PRTN3 observed across multiple cohorts, we further investigated its role in intervertebral disc degeneration (IDD) and diabetes mellitus (DM)." (PMID 40756519, 2025).
chronic obstructive pulmonary disease (12 papers, 2018 to 2025). A chronic and progressive lung disorder characterized by the loss of elasticity of the bronchial tree and the air sacs, destruction of the air sacs wall, thickening of the bronchial wall, and mucous accumulation in the bronchial tree. "PRTN3 has been proposed as a therapeutic target for example in chronic obstructive pulmonary disease, an inflammatory condition associated with neutrophilic inflammation." (PMID 33374674, 2020). "Neutrophil proteinase 3 (PR3) is an important drug target for inflammatory lung diseases such as chronic obstructive pulmonary disease and cystic fibrosis." (PMID 38917138, 2024). "Stimulated by various respiratory inflammatory diseases, such as asthma and chronic obstructive pulmonary disease (COPD), after activation, they release proinflammatory ROS and serine proteases, including neutrophil elastase and proteinase-3." (PMID 33763174, 2021). "These enzymes particularly neutrophil elastase (NE) and proteinase 3 (PR3), have been shown to induce emphysematous and airway changes similar to features of chronic obstructive pulmonary disease (COPD) when instilled into the lungs of experimental animals." (PMID 37573351, 2023).
lung disease (12 papers, 2006 to 2025). "NSPs include neutrophil elastase, proteinase 3 and cathepsin G. An imbalance between NSPs and their antiproteases has been observed in people with CF lung disease and people with NCFBE." (PMID 39293854, 2024). "Neutrophil elastase and proteinase 3 are both neutrophil serine proteinases which are released by neutrophils and play a part in the pathophysiology of various lung diseases." (PMID 38982423, 2024). "Peptidase inhibitor 3 (PI3) inhibits neutrophil elastase and proteinase-3, and has a potential role in skin and lung diseases as well as in cancer." (PMID 16719916, 2006). "There is a relationship between aPWV, lung disease and proteinase-3 activity." (PMID 38515138, 2024). "In addition, neutrophils, one type of granulocytes, secrete serine proteases including neutrophil elastase, cathepsin G and proteinase-3, as well as MMP-8 and MMP-9, which may lead to destruction of the alveolar tissue and increase the risk of lung disease." (PMID 30400967, 2018).
lupus nephritis (12 papers, 2008 to 2025). Glomerulonephritis in the context of systemic lupus erythematosus. "These include scleroderma overlap syndromes with features of lupus nephritis, myeloperoxidase ANCA, proteinase 3 ANCA-associated GN or crescentic GN." (PMID 18474117, 2008). "New studies also indicate that Annexin A1 in lupus nephritis is a component of NETs that seems of interest in view of the analogy with several other auto-immune conditions, such as small vessel vasculitis, in which components of NETs (i.e., MPO or proteinase 3) serve as antigens for antibodies." (PMID 29751523, 2018).
viral infection (12 papers, 2005 to 2025). "Neutrophil activation derived autoantigens (MPO, PRTN3, and PADI4) were prominently increased in blood of both SARS-CoV-1 and SARS-CoV-2 viral infections, while TSHR and PTPRN2 autoantigens were specifically increased in SARS-CoV-2." (PMID 34276672, 2021). "PRTN3, ELANE and CSTG were significantly increased in all three viral infection cohorts." (PMID 33868254, 2021).
IgA nephropathy (11 papers, 2014 to 2025). "Although the possibility of antineutrophilic cytoplasmic antibody (ANCA)-associated nephritis with superimposed IgA nephropathy was considered, negative myeloperoxidase and proteinase 3 antibody tests led to a final diagnosis of IgA nephropathy." (PMID 37680420, 2023).
Obesity (11 papers, 2014 to 2025). Accumulation of substantial excess body fat. "Integrated protein-metabolite network analysis identified OSBPL10, CUL2, and PRTN3 as potential regulators of lipid metabolism and insulin resistance, offering insights into obesity-associated metabolic dysfunction." (PMID 40822952, 2025). "The patient had a body mass index of 31.9, which is classified as obesity (height: 177 cm; body weight: 100 kg), and his anti-proteinase-3 (PR3) antibody level was greater than 100 U/mL." (PMID 40703284, 2025).
autoimmune vasculitis (10 papers, 2018 to 2025). An autoimmune form of vasculitis. "Since several patients who were severely or critically ill had thromboembolic and vascular events, we also analyzed the same 73 patients for Myeloperoxidase (MPO) and Proteinase 3 (PR3) antibodies, as these antibodies are associated with autoimmune vasculitis." (PMID 34521836, 2021). "Seventy-five patients with clinically suspected autoimmune vasculitis (AIV) and 25 healthy volunteers were also tested for anti-myeloperoxidase and anti-proteinase 3 antibodies using IIF, the AtheNA Multi-Lyte® AIV system, and enzyme-linked immunosorbent assay (ELISA)." (PMID 37293321, 2023).